EGFR (epidermal growth factor receptor)
Diseases named in the same sentence as EGFR in open-access papers (continued):
Sharing a sentence is not in itself a finding about the gene and the disease.
cancer (continued). "Epidermal growth factor receptor (EGFR)-mutated NSCLC are essentially ‘immune-excluded’ cancers." (PMID 33574893, 2020). "This was Central Carbon metabolism in Cancer with three associated genes EGFR, NTRK3, and SLC7A5." (PMID 33317464, 2020). "Mutations in EGFR may determine the responsiveness of some cancers to treatment with different chemotherapies, and PNA clamps have been examined to help analyze mutations in the DNA encoding this receptor." (PMID 32059456, 2020). "Detecting DNA from a cancer-specific gene, such as the EGFR mutant allele, may become difficult if many inflammatory cells are included in the sputum." (PMID 32033355, 2020). "EGFR overexpression, often due to genetic alterations, has been firmly and consistently associated with carcinogenesis, and EGFR itself recognized as a potential target of an important therapeutic approach to cancer." (PMID 32256580, 2020). "Interestingly, cancer cells expressing EGFR variant III are less sensitive to cetuximab even though the cetuximab binding epitope remains intact." (PMID 32698317, 2020). "It has also been shown that lactate (produced by MET/EGFR TKI-resistant cancer cells) enhances the production/secretion of HGF by cancer-associated fibroblasts, which in turn activates MET-dependent signalling pathways in cancer cells, causing adaptive resistance to MET inhibitors." (PMID 33271944, 2020). "Similarly, in EGFR-mutated NSCLC cancer progressing to anti-EGFR TKIs, a number of studies have evaluated the expression of resistance mutations and rearrangements, such the EGFR T790M secondary mutation or MET amplification." (PMID 32460897, 2020). "However, only lapatinib targets cancers that overexpress ERBB2/HER2; erlotinib and gefitinib act in cancers with mutated or overactive EGFR." (PMID 32366937, 2020). "Overexpression of EGFR is associated with poorer survival in many cancers." (PMID 32413049, 2020). "While cancer-specific exon–exon junctions may indeed be a source of neoepitopes, their sharedness across individuals and occurrence in cancer-relevant loci (e.g. EGFR, MUC16) are suggestive of underlying but as-of-yet unexplored biology." (PMID 34316681, 2020). "Mutations in the ectodomain (ECD) of EGFR have been well-documented in other cancers." (PMID 32069320, 2020). "To date, EGFR has been linked to several malignant phenotypes of human cancers, including proliferation, inflammatory response, DNA repair, therapeutic resistance, and poor clinical outcomes in patients with cancer." (PMID 32093123, 2020). "Aberrantly expressed EGFr, inappropriate activation of intracellular signaling mediated by mutated EGFr, or both can induce cancer initiation and progression, and EGFr TKIs are current first‐line therapies for various cancers linked to EGFr signaling." (PMID 32652816, 2020). "However, these targeted cancer drugs are ineffective for patients with low EGFR expression or who have mutations in the extracellular domain of EGFR, and thus it is necessary to identify new therapeutic targets in addition to EGFR." (PMID 32398959, 2020). "This was of particular interest as both amplifications and mutations in EGFR have been shown to be drivers in many cancer types and may confer efficacy of treatment with tyrosine kinase inhibitors." (PMID 32570879, 2020). "Abnormal EGFR overexpression and signaling are associated with malignant tumors of the lung, pancreas, brain, bladder, breast, prostate, and other cancers." (PMID 32194412, 2020). "Additionally, septins have been increasingly linked to cancer oncogene expression, including EGFR, HER2 and the HIF-1α/angiogenesis axis." (PMID 32094384, 2020). "Additionally, overexpression of EGFR was associated with less potent responses to cancer immunotherapy in NSCLC and neuroblastoma." (PMID 32630675, 2020).
cancer (continued). "Each two-drug combination showed synergy at three different DEQ ratios, suggesting that inhibition of any two proximal signaling proteins may be an effective therapeutic regimen to treat EGFR-mutated cancer." (PMID 32897190, 2020). "To further understand the upstream regulation of ILF3, we next determined whether the activation of EGFR, which is overexpressed or mutated in many cancer types, including CRC, has an effect on ILF3 expression." (PMID 31772275, 2020). "Therefore, genetic alterations causing aberrant activity of EGFR have been reported to be implicated in the development of many human cancers, such as lung, colorectal, skin, breast, prostate, kidney, pancreas, ovary, and brain cancers." (PMID 33171861, 2020). "Although the number of cancer somatic mutations has been increasing at a fascinating speed, our knowledge of distinguishing driver mutations from passenger mutations remains limited, even in best-studied cancer genes such as EGFR and BRAF." (PMID 32079540, 2020). "Based on the gene expression analysis, FD extract had reduced the expression of the TWIST1 and RAC1 genes associated with epithelial-mesenchymal transition (EMT) and had significantly downregulated the COX-2 and EGFR genes associated with cancer angiogenesis, metastasis, and chemoresistance." (PMID 32104177, 2020). "According to the database of COSMIC, the world's largest and most comprehensive resource for exploring the somatic mutations in human cancer, chromosome 7 consists of lots of well-known cancer-related somatic mutations, including EGFR, BRAF, CDK6, MET, T1F1, and so on." (PMID 32695679, 2020). "EGFR becomes essential when EGFR is mutated in cancer cells because of oncogene addiction." (PMID 32645997, 2020). "Furthermore, patients with cancers that harbor mouse double minute 2 homolog (MDM2) amplification or EGFR mutations have increased the risk of HPD after anti-PD-1/PD-L1 treatment." (PMID 32792499, 2020). "Overexpression of EGFR was found associated with poor cancer prognosis." (PMID 33363566, 2020). "However, EGFR has been aberrantly expressed in many cancers due to mutations associated with poor cancer prognosis." (PMID 33014289, 2020). "Studies have demonstrated that nuclear EGFR (nEGFR) acts as a transcription factor regulator involved in tumorigenesis, is associated with poorer outcomes in many cancers, and is implicated in resistance to radiation and anti-EGFR therapies, including cetuximab." (PMID 32295603, 2020). "As with STAT3, activation of EGFR signalling may induce STAT5 phosphorylation in HPV-associated cancers." (PMID 32899142, 2020). "Cancers with EGFR mutations (EGFR-mutated cancers) rely on EGFR signaling for growth." (PMID 32070026, 2020). "This ‘initial survival’ of cancer cells from targeted therapy against driver oncogenes has recently been highlighted in epidermal growth factor receptor (EGFR)-mutated tumors, and the Notch-3/β-catenin pathway or AXL has been shown to play a key role in this survival." (PMID 31900393, 2020). "Moreover, one reaction of these patients to EGFR inhibitor cancer therapy is the T766M mutation that increases the affinity of the EGFR-L834R oncoprotein by more than 10-fold." (PMID 33333800, 2020). "Studying the proteomic cargo of EVs revealed the proteins associated with platelet activation, EGFR, Rap1, integrin, and microRNA signaling that could regulate metastasis and cancer progression." (PMID 32916986, 2020). "Furthermore, we discovered that some of the predicted target genes of Oroxylum indicum were associated with cancer, such as EGFR, PIM1, ESR1/2, and MAPK8/10." (PMID 32733583, 2020). "EGFR is inappropriately activated in cancer mainly because of amplification and point mutations." (PMID 33317464, 2020). "However, T790M mutation, which raised resistance in TKIs caused by EGFR, has become a major challenge in cancer treatment." (PMID 32121322, 2020).
cancer (continued). "The bioinformatics analysis showed that hsa_circ_0005875 may function as miRNA sponges and was predicted to be associated with the biological process of the epidermal growth factor receptor signaling pathway, involving in cancer invasion and metastasis." (PMID 33193877, 2020). "Notably, it has been reported that upregulation of ERRFI1 is associated with acquired resistance to the EGFR tyrosine kinase inhibitor (TKI) in a cancer cell line." (PMID 31969149, 2020). "Mediation analysis revealed that the association between lower lobe cancer and higher all-cause mortality could be explained by an indirect pathway through EGFR mutations (percent mediated = 17.3%, p = 0.005)." (PMID 32913267, 2020). "Previous studies had shown that EGFR inhibitors treatment induced autophagy in multiple cancer cell lines, but the specific mechanism underlying this process was unknown." (PMID 33287140, 2020). "However, in this study we show that loss of EGFR results in the resistance of cancer cells to TRAIL." (PMID 32413049, 2020). "Overexpression of VEGF by this pathway is associated with cancer cell resistance to anti-EGFR." (PMID 33096664, 2020). "Cancer cells that overexpress EGFR and/or ErbB2 are susceptible to their inhibition by Lapatinib." (PMID 33348877, 2020). "EGFR mutation is detectable if the carcinoma cell content is more than 1.5%, but cytology maybe more sensitive at a lower cellular content." (PMID 32033355, 2020). "IL-8 blockade may also have a role as an adjunct to cancer therapy to decrease rash associated with epidermal growth factor receptor (EGFR) inhibitors." (PMID 31488216, 2019). "Furthermore, the epidermal growth factor receptor (EGFR) is often mutated and overexpressed in cancers including in GBM where increased wild type EGFR can often be observed." (PMID 31795417, 2019). "In cancer, acquired mutations disrupt the normal functioning of the EGFR/ERK pathway." (PMID 31016574, 2019). "Alterations of EGFR (overexpression or kinase-activating somatic mutations) are common in cancers." (PMID 31121829, 2019). "Jointly, these data imply that coexisting mutations in EGFR itself or in other cancer-drivers at baseline may potentially impair the efficacy of EGFR-TKIs and explain why some TKI-treated NSCLCs are intrinsically resistant." (PMID 31266248, 2019). "It should be noted that these EGFR regulators have been implicated in human cancers." (PMID 30974867, 2019). "However, cancer patients with EGFR mutations usually gain resistance to tyrosine kinase inhibitors, reducing the average time to progression of disease to a few months." (PMID 31013819, 2019). "Moreover, EGFR and K-Ras mutations are mutually exclusive in NSCLC with the emergence of K-Ras mutations associated with resistance to EGFR-targeted cancer therapies." (PMID 31792060, 2019). "EGFR is frequently hyperactivated in human cancers via mutation and/or overexpression." (PMID 31164594, 2019). "A retrospective cohort study of 88 NSCLC patients with EGFR mutation positive treated with gefitinib (n=59), erlotinib (n=22), and afatinib (n=7) was performed in national cancer hospital in Indonesia.Inclusion criteria were stage IIIb or IV NSCLC with adenocarcinoma subtype." (PMID 31526459, 2019). "The previous finding that EGFR signaling could activate canonical Wnt/β-catenin pathways in cancer prompted us to further investigate the mechanism underlying such a crosstalk." (PMID 30177836, 2019). "This increased EGFR activity can induce cell proliferation and promote the repair of DNA damage caused by chemoradiotherapy, which results in therapeutic resistance and ultimately cancer progression." (PMID 30700700, 2019). "Comparing the cancer cell fraction (CCF) of EGFR mutations across different stages demonstrated that EGFR mutations were only present as minor subclones in AAH (mean CCF = 0.11), which became major subclones in AIS (mean CCF = 0.66), MIA (mean CCF = 0.54) and ADC (mean CCF = 0.71)." (PMID 31278276, 2019).
cancer (continued). "Interestingly, cancer patients treated with EGFR inhibitors are more susceptible to S. aureus, a pathogen that is neutralized by Th17 lymphocytes." (PMID 31744223, 2019). "Furthermore, nuclear EGFR is highly associated with disease progression, worse overall survival in numerous types of cancer." (PMID 30971297, 2019). "A cancer spheroid array chip was developed by modifying a micropillar and microwell structure to improve the evaluation of drugs targeting specific mutations such as phosphor-epidermal growth factor receptor (p-EGFR)." (PMID 31614722, 2019). "EGFR TKIs have clearly been clinically efficacious in responsive types of cancers (expressing kinase-activating mutations in EGFR), however, the benefits are often limited to improving the progression free survival (PSF) and quality of life rather than the overall survival (OS)." (PMID 31508364, 2019). "Overexpression and/or mutation of EGFR is characteristic for numerous cancers." (PMID 30871021, 2019). "The target-binding specificity of 89Zr-DFO-ZEGFR:03115 was evaluated in a panel of cancer cell lines with different degrees of EGFR expression, demonstrating that the cell-associated radioactivity was consistent with the measured total EGFR protein expression level in each cell line." (PMID 30213849, 2019). "Therefore, abnormal expression or an activating mutation of the EGFR gene will irreversibly lead to cancer." (PMID 31367332, 2019). "Several studies have addressed whether possible co-mutations in alternative cancer-drivers could represent mechanisms of inherent resistance to EGFR-TKIs." (PMID 31266248, 2019). "Overexpression and somatic mutations of EGFR result in enhanced cancer cell survival." (PMID 31527477, 2019). "For instance, EGFR (epidermal growth factor receptor) mutation testing using ctDNAs was approved as a companion in vitro diagnostic, while ctDNA testing has been required for the pre-analytical and analytical phase in the other cancer." (PMID 31480647, 2019). "Moreover, EGCG inhibits the proliferation of cancer cells through epidermal growth factor receptor (EGFR) and ERK pathways and downregulates cell cycle-associated protein, resulting in apoptosis in ATC cell line, ARO." (PMID 30634497, 2019). "Moreover, AMPK activation is shown to trigger autophagy and degradation of multiple growth factor receptors (i.e., epidermal growth factor receptor (EGFR) and platelet-derived growth factor receptor α (PDGFRα)), thereby causing cancer cell inhibition." (PMID 31727877, 2019). "In breast and other cancers radiation-induced proliferation has been linked with activation of EGFR and downstream components of the mitogen-activated protein kinase (MAPK) cascade, including phospholipase-C, Ras, and Raf-1 and can be considered an important cytoprotective response." (PMID 30987655, 2019). "Furthermore, harmine also enhanced the anti‐cancer activity of AZD9291 in HCC827 cells harbouring EGFR Del19 mutation, which are sensitive to AZD9291 treatment." (PMID 31454149, 2019). "While we can predict the drug sensitivity of the majority of cancer‐associated EGFR variants, there are less common EGFR variants 16, 17, 18, 19, 20, 21, 22, 23, 24 that remain poorly characterized, and thus, their clinical relevance remains unclear." (PMID 31314158, 2019). "What is the exact mechanism underlying EGFR's pro-survival function in cancer cells?" (PMID 31508364, 2019). "Upregulation of EGFR activity due to over-expression or mutation is widely implicated in cancer." (PMID 31536605, 2019). "Thus, ORNi-PCR with cDNA can simultaneously detect the two EGFR single-nucleotide mutations if cancer cells harboring these mutations constitute more than 0.2% of the total cell number." (PMID 31426517, 2019). "In cancer, EGFR is often mutated, leading to enhanced or sustained receptor signaling." (PMID 29377763, 2018).
cancer (continued). "Even if further studies are needed, we propose that NP tethering could expand application of the anti-EGFR antibody to a wider number of cancer patients including the KRAS-mutated ones, currently suffering from poor prognosis." (PMID 30287819, 2018). "This approach could be effective not only in RAS-mutant-driven cancers but also those driven by mutations in EGFR, and, by extension, possibly in tumors driven by other upstream receptor tyrosine kinases, such as MET and ALK." (PMID 30590030, 2018). "In addition, the EMT has been implicated in several other cancer-related phenotypes, for example, in cancers that acquired resistance either to the EGFR inhibitor gefitinib or to the HER2 receptor inhibitor trastuzumab." (PMID 30059005, 2018). "Small molecules that degrade Ras independent of β-catenin may able to be used in treatments for cancers caused by aberrant EGFR and Ras." (PMID 29884842, 2018). "Here we report that this signature could be detected in the cetuximab-associated skin inflammation manifesting in cancer patients after 2/3 weeks from the first systemic administration of this anti-EGFR drug." (PMID 30200670, 2018). "In addition, we found that morphologic characteristics were different in cancer tissues with high mEGFR expression, high nEGFR expression and EGFR mutations." (PMID 29950164, 2018). "Mutations in EGFR are associated with a number of cancers, but the precise role of EGFR in HCC is still unknown." (PMID 30344796, 2018). "However, previous preclinical work utilizing mice with dominant-negative (inactivating) EGFR mutations paradoxically showed an increase in cancer incidence." (PMID 29904166, 2018). "Although compared to traditional platinum-based combination chemotherapy, EGFR-TKIs provided significant clinical benefits and became a cornerstone treatment strategy for various cancers including NSCLC with EGFR-activating mutations, the low safety profiles of these agents should be acknowledged." (PMID 30404198, 2018). "However, the EGFR mutation was estimated to be present in all the cancer cells, whereas the PIK3CA mutation was estimated to be present in only 38% of the cancer cells." (PMID 29738578, 2018). "We aimed to determine whether EGFR expression in the different microdissected areas was related to EGFR gene alterations, i.e. cancer hotspot point mutations, exon 19 deletion, or gene copy-number variations." (PMID 29492209, 2018). "Recently, studies have reported that T790M might coexist with EGFR-activating mutations in the same cancer sample before EGFR-TKI treatment, despite the low incidence." (PMID 29581983, 2018). "The EL2BH nanobody could be used for nanoparticle construction and delivery of a diagnostic or therapeutic cargo to EGFR overexpressing cancer cells." (PMID 30348204, 2018). "For EGFR-TKIs, down-regulation of cellular apoptosis may be a possible cause of cancer cell resistance." (PMID 30404198, 2018). "We showed that, when ML TNBC MDA-MB-231 and BT-549 cells, expressing EGFR on their surface, are grown in 3D cultures or are injected in nude mice to form tumors, EGFR is associated with integrin αvβ3, one of the principal adhesion molecules expressed on cancer cells." (PMID 30428522, 2018). "Interestingly, the prolonged use of EGFR tyrosine kinase inhibitors is associated with a common side effect of skin inflammatory rash in cancer patients." (PMID 30093649, 2018). "Thus, an understanding of the mechanism(s) underlying EGFR’s kinase-independent (KID) functions offers great potential for the development of effective therapeutic approaches for cancer treatment." (PMID 29358623, 2018).